STAT3 (signal transducer and activator of transcription 3)
Diseases named in the same sentence as STAT3 in open-access papers (continued):
Sharing a sentence is not in itself a finding about the gene and the disease.
cancer (continued). "While muscle STAT3 contributes to muscle wasting in several models of cancer cachexia, this pathway is also activated in rodent models of muscle growth." (PMID 27449092, 2016). "Phosphorylated STAT3 under hypoxic conditions has been shown in multiple cancer cell lines to stabilize and simultaneously bind with HIF-1α to separate sites on the VEGF promoter, in order to maximally induce expression." (PMID 27529341, 2016). "IL-6 is an activator of Jak2/STAT3 signaling pathway which is involved in the development of cancers and EMT." (PMID 27121055, 2016). "In this pathway, STAT3 is the most recognized oncogene and frequently is activated in human cancers." (PMID 26768588, 2016). "At the cross road of cancer and inflammation, the STAT3 and MAPK pathways have been reported as crucial for CSC growth and their acquired EMT characteristics during metastasis." (PMID 26762586, 2016). "Upregulated FOXD3 protein levels and downregulated phosphorylated STAT3 (Tyr705) protein levels were identified by immunoblot analysis in nuclear extracts of clinical cancer samples obtained from patients who regularly used aspirin." (PMID 26898989, 2016). "The biological effects of TGFBR2 and STAT3 have been extensively studied in cancer and the immune system." (PMID 26972162, 2016). "To directly target persistent STAT3 signaling in cancer cells, we recent developed a novel small molecular STAT3 inhibitor LY5, which was derived from LLL12 by an in silico site-directed Fragment-based drug design." (PMID 26883202, 2016). "Our finding mirrors previous reports of constitutive STAT3 activation in response to aberrant upstream tyrosine kinase activities in a broad spectrum of human cancers." (PMID 27845909, 2016). "Bcl-xL is one of the anti-apoptotic proteins regulated by STAT3 in cancer cells, and its expression can be suppressed using specific inhibitors of the STAT3 pathway." (PMID 27409672, 2016). "Recent studies have suggested a correlation between autophagy and the activity of STAT3 in human cancer." (PMID 27474168, 2016). "Transcriptional factors, STAT3 and NF-κB, play crucial roles in carcinogenesis, cancer cell proliferation and survival in many types of cancers." (PMID 27074565, 2016). "Adiponectin also inhibits leptin-induced metastasis by downregulating JAK/STAT3 pathway, displaying an inverse correlation with cancer development." (PMID 27119501, 2016). "Grim19 has been primarily investigated in apoptosis and cancer because it diminishes STAT3 activation." (PMID 27258062, 2016). "LY5 has the potential to become a drug candidate for targeting cancer cells with constitutively activated STAT3 due to its ability to inhibit STAT3 phosphorylation and suppress growth." (PMID 26883202, 2016). "NF-kB and STAT3 are known to mediate the expression of many genes that influence growth and inflammation and are often upregulated in cancer." (PMID 28536612, 2016). "Recent studies found that niclosamide is a potential anticancer agent by inhibits multiple signaling pathways including the Wnt/β-catenin, mTORC1, STAT3, NF-κB and Notch signaling pathways in cancer cells." (PMID 27363012, 2016). "Leptin-induced activation of STAT3 regulates several genes involved in cancer, which include cyclin D1, cyclooxygenase (COX)-2, VEGF, human telomerase reverse transcriptase (hTERT), Survivin and leptin." (PMID 27472371, 2016). "Aberrant IL-6/STAT3 signaling in cancer cells have emerged as a major mechanism for cancer initiation and development." (PMID 27938379, 2016). "Overall, these data demonstrate that reductions in STAT3 signaling, independent to NF-κB, were accompanied by improvements in protein turnover regulation during the progression of cancer cachexia in ApcMin/+ mice." (PMID 27449092, 2016). "Retrospective studies have established that STAT3 expression or phospho-STAT3 (pSTAT3 or activated STAT3) are poor prognostic markers for many cancers including PC." (PMID 27435207, 2016).
cancer (continued). "A growing body of cancer research evidence has indicated that activation of gp130/STAT3 induces the expression of multiple survival, proliferation and antiapoptosis associated genes, such as MCL-1, Bcl-2, Bcl-XL, Survivin and cyclin D1." (PMID 27537522, 2016). "A role of S1P in regulating NF-κB and STAT3 activation, two key signaling pathways that link cancer with inflammation, has been long suspected, but only recently uncovered." (PMID 27800303, 2016). "The rs4796793 SNP, together with rs744166 that is in high LD with rs4796793 (r2>0.8), is the most widely studied STAT3 SNP in various cancers." (PMID 27049718, 2016). "We recently reported that active STAT3 is often present in cancer, stromal and endothelial cells in human PDAC tissues, and in tumors arising in the KRC mouse model." (PMID 26586478, 2016). "As a critical transcription factor, STAT3 is also important for normal biological activity in addition to cancer cells." (PMID 26814430, 2016). "Treatment with peptide 520 suppressed JAK2, phospho-STAT3, and Bcl-xL, resulting in cancer cell death." (PMID 27409672, 2016). "Pharmacological inhibition of IL-6/STAT3 activation by a JAK inhibitor restrained cancer stem cell growth in vitro and inhibited self-renewal in vivo." (PMID 27732936, 2016). "Such an interaction between RNLS and STAT3 has important implications regarding the role of RNLS signaling in the pathogenesis of cancer." (PMID 26972355, 2016). "In cancer cells with a low Warburg effect, STAT3 is constitutively acetylated and undergoes steady-state translocation into mitochondria, where it is constitutively involved in energy metabolism." (PMID 28004755, 2016). "It has been well established that STAT3 can be activated in cancer cells, which makes itself an attractive target for anti-cancer therapy." (PMID 27101310, 2016). "In summary, the apoptosis of cancer cells regulated by HCCR expression was dependent on STAT3 activity." (PMID 27052330, 2016). "Activation of Stat3 signalling is shown to be correlated with the resistance of cancer cells to cisplatin‐induced apoptosis, and suppression of STAT3 by siRNAs increases the chemotherapeutic sensitivity of cisplatin‐resistant non‐small‐cell lung cancer cells." (PMID 27374471, 2016). "Overexpression of constitutively active STAT3 partly reversed the anti cancer effects of (−)-oleocanthal, which inhibited STAT3 activation by decreasing the activities of JAK1 and JAK2 and increasing the activity of SHP-1." (PMID 27259268, 2016). "The interaction of NF-κB and STAT3 has been found in some human cancers, including colon, gastric, and liver." (PMID 27602766, 2016). "It is becoming clear that any efforts to block STAT3 activity in cancer cells are likely to have synergistic and/or deleterious off-target effects on host immune responses mediated through NK cells." (PMID 27148255, 2016). "There is evidence to suggest that abnormal STAT3 signaling promotes progression of human cancers by either inhibiting apoptosis or inducing cell proliferation, angiogenesis and metastasis." (PMID 27486982, 2016). "STAT3 is constitutively active and associated with poor clinical prognosis in several cancers and consequently, STAT3 is an attractive target for pharmacologic intervention in cancer patients." (PMID 27049829, 2016). "For example, natural products inhibit JAK2/STAT3 signaling and induce apoptosis in various cancer cells." (PMID 26755649, 2016). "Most of the studies have revealed anti-cancer effects of Cucurbitacin D via induction of apoptosis and suppression of constitutive activation of NF-κB and STAT3." (PMID 27824155, 2016). "Signal Transducer and Activator of Transcription 3 (STAT3) regulates various aspects of cancer cell biology, including apoptosis, proliferation, and survival." (PMID 26784177, 2016). "Late phase activation of STAT3 is important for virus persistence and potentiating cancer-like properties of infected cells." (PMID 27458446, 2016).
cancer (continued). "The IL-6/STAT3/NF-κB positive feedback loop links inflammation to cancer and maintains cells at a transformed state." (PMID 27248826, 2016). "Previous studies have demonstrated that IL10 acts as a suppressor of the immune system, and an activator of the JAK/STAT3 pathway in cancer cells." (PMID 26956044, 2016). "Another small molecule, STATTIC, discovered by high throughput screening, has shown to potently inhibit activation, dimerization, nuclear translocation of STAT3, and to increase apoptosis in STAT3-expressing cancer cell lines." (PMID 27166190, 2016). "IL-6 is characterized as a COX-2-dependent cytokine necessary to activate numerous oncogenic signals acting downstream of COX-2 in cancer cells via activating STAT3 (signal transducer and activator of transcription 3)." (PMID 27385366, 2016). "The Signal Transducer and Activator of Transcription 3 (STAT3) oncogene is a master regulator of many human cancers, and a well-recognized target for therapeutic intervention." (PMID 26942696, 2016). "Because of its significance in carcinogenesis and poor clinical outcomes, STAT3 has been developed as an ideal drug target for various cancer treatment." (PMID 27705908, 2016). "Validated targets were found in pathways predictably relating to cancer, but also FoxO signalling—including STAT3 in both pathways and forkhead box protein (FOX) O1 in the latter." (PMID 27529341, 2016). "Napabucasin (BBI608) is a newly found small molecule with the ability to inhibit gene transcription of STAT3, which was able to suppress cancer stemness properties and induce cell death." (PMID 26899963, 2016). "Our results also suggest the possibility of crosstalk between these miRNAs and key inflammatory-/cancer-related factors, such as STAT3, and other STATs and cytokines." (PMID 27683108, 2016). "Targeting the STAT3 pathway is considered one of the key therapeutic approaches to block cancer proliferation and metastasis." (PMID 27657126, 2016). "STAT3, another member of our network has also been heavily involved in cancers where STAT1 is upregulated." (PMID 27295045, 2016). "Several cytokines and the activation of PI3K and STAT3 pathway have been reported to increase PD-L1 expression in some cancers." (PMID 26761210, 2016). "The main purpose of this study was to investigate the level of STAT3 activation subsequent to isolation of CSLCs from GC, which was representative of chronic inflammationinduced cancers." (PMID 26862521, 2016). "Dysregulation of Annexin A2 and STAT3 has been reported to take effects on cancer progression, metastasis, and prognosis, particularly in CRC." (PMID 27274723, 2016). "The inhibitory activity of silibinin against the phosphorylation of STAT3 has been demonstrated in preclinical studies in various cancers; however, further clinical trials are needed to fully characterize silibinin activity as a STAT3 inhibitor." (PMID 27657126, 2016). "Signal transducer and activator of transcription 3 (STAT3) can negatively regulate E-cadherin and positively modulate N-cadherin and has become a promising target for cancer immunotherapy." (PMID 27121311, 2016). "As such, targeting STAT3 is a potentially feasible approach to the treatment of cancer and several inhibitors of STAT3 are currently under development." (PMID 27367272, 2016). "Many types of cancer cells can secrete IL-6 because of the constitutively activated STAT3 and NF-κB." (PMID 27074565, 2016). "There is ample evidence for the role of STAT3 in cancer, with its activation contributing to cancers in the head and neck, breast, prostate, thyroid, skin (melanoma), and GBM." (PMID 27148537, 2016). "In contrast, chronic SH-4-54 treatment of representative ERα-positive cells that initially respond to STAT5 signals results in STAT3 activation and up-regulation of xCT, potentially leading to a more aggressive cancer subtype." (PMID 27513743, 2016).
cancer (continued). "Physiologically, is a target of STAT3, but in cancer its promoter is methylated, and consequently its down-modulation alters microRNA-mediated anti-inflammatory circuit." (PMID 27551267, 2016). "The interleukin-6 (IL-6)/JAK/STAT3 signaling pathway has recently been shown to have a central role in inflammation-mediated cancers, such as those of the liver and stomach." (PMID 27049718, 2016). "Stat3 has also been found to be involved in cancer cell growth, survival, invasion, and migration through regulation of the expression of E-cadherin, VEGF, and MMPs." (PMID 27460364, 2016). "IL-6 mediated activation of transcription factor STAT3 (to its activated form p-STAT3) is a common oncogenic process and is one of the mechanisms through which chronic inflammation contributes to cancer development and progression." (PMID 26837852, 2016). "The positive feedback loop of two key inflammatory signaling pathways, NF-kB and IL-6/STAT3, has been suggested as a link between inflammation and cancer in previous studies." (PMID 27609180, 2016). "STAT3 has been found to be constitutively activated in various types of cancer cell lines and tumors." (PMID 27344974, 2016). "Hyperactivation of STAT3 via constitutive phosphorylation of tyrosine 705 (Y705) is common in most human cancers, including head and neck squamous carcinoma (HNSCC)." (PMID 27855189, 2016). "It has been reported that transcriptional activation of miR-21 by STAT3 leads to the induction of a stable transformed state in cancer cell lines." (PMID 27323401, 2016). "We reported that neuronal S1P/S1PR1/STAT3 signaling plays an important role in distinct conditions of abnormal feeding behavior, such as obesity and cancer-induced anorexia." (PMID 28039439, 2016). "STAT3 is known to promote cell proliferation and angiogenesis and play a role in the invasiveness and metastatic potential of cancers." (PMID 27052330, 2016). "Cumulative evidence has established that STAT3 plays a critical role in the development and mediation of oncogenic signaling in many different cancers." (PMID 27190500, 2016). "The activation of STAT3 is essential for the proliferation and metastasis of a wide range of cancer, and its high expression is indicative of a poor prognosis." (PMID 27657126, 2016). "Another target is STAT3, which is a point of convergence for many tyrosine kinase signal pathways and is constitutively activated at high frequency in a wide range of cancers." (PMID 27494878, 2016). "STAT3 regulates the expansion of myeloid-derived suppressor cells (MDSCs) duringinflammation, infection and cancer." (PMID 26848037, 2016). "Because activation of STAT3 occurs in cancers with activated Src kinase, we examined regulation of Src kinase in MDA-MB-231 cells overexpressing or suppressing AF1q." (PMID 27259262, 2016). "More importantly, STAT3-C overexpression partially reversed the (−)-oleocanthal-induced increase in apoptosis and inhibition of invasion in HCC cells, indicating that its anti-cancer effects were partly dependent on STAT3 activation." (PMID 27259268, 2016). "Many studies had shown that niclosamide blocked cancer cells proliferation in a number of tumors types by suppressing the activities of several oncogenic pathways, including NF-kB, STAT3, notch and Wnt." (PMID 26917416, 2016). "Our data demonstrate that HCCR is probably involved in apoptosis and cancer growth and that it functions as a p-STAT3 stimulator in a positive feedback loop model." (PMID 27052330, 2016). "More importantly, we successfully proved that miR-148a directly binds CCK-BR and conduct its anti-cancer effects via inactivating STAT3 and Akt, as well as subsequent modulation of their downstream gene products." (PMID 27518872, 2016). "HNSCC was the first human cancer demonstrated to depend on constitutively activated STAT3 for growth." (PMID 27027445, 2016). "We provided evidence that downregulation of Stat3 was critical for the inhibition of cancer cells in vivo." (PMID 27460364, 2016).
cancer (continued). "Axin, β-catenin, Adenomatous polyposis coli (APC) and STAT3/5 is the integral component of the Wnt/β-catenin signaling pathway which plays a critical role in cell growth, differentiation and cancer process." (PMID 27613831, 2016). "The increase in cancer cell proliferation is mediated by STAT3-activated production of Bcl-xL, Bcl-2 and c-IAP2, which are also activated by NF-κB." (PMID 31051015, 2016). "Bcl family (Bcl-2, Mcl-1), which are known to be crucial for cancer cell survival, are prominent targets for STAT3 and NFκB, and down-regulated as a consequence of STAT3 and NFκB inhibition." (PMID 27539371, 2016). "Metformin reduces inflammation through improving metabolic disturbances or through inhibiting the proinflammatory cancer-promoting nuclear factor κB and STAT3 pathways." (PMID 27486978, 2016). "Taken together, inflammatory environment within tumors promotes cancer development by activating NF-κB and STAT3 signaling and upregulating pro-survival and cell cycle-driving genes." (PMID 31051015, 2016). "Among several oncogenic pathways, we found that HER2 promotes radiation-induced activation of STAT3, one of the key signaling molecules in multiple radioresistant cancers." (PMID 26755645, 2016). "There are seven members in STAT family; in particular, STAT1 and STAT3 play important roles in cancer cells." (PMID 26909593, 2016). "We also found that miR-148a-mediated anti-cancer effects are dependent on the inhibition of STAT3 and Akt activation, which subsequently regulates the pathways involved in cell proliferation and migration." (PMID 27518872, 2016). "We tested the influence of apigenin on the expression of AP-1, NF-κB, STAT-3, and cMyc, which are important signal pathway molecules in cancer cells." (PMID 27203387, 2016). "At the same time, STAT3 is also involved in cancer cells functions, thus making it a promising target for cancer immunotherapy." (PMID 26900950, 2016). "Major signaling pathways frequently upregulated in chemoresistant cells and important in the maintenance of cancer stem cells (CSCs) include Wnt/β-catenin, mTOR, and STAT3." (PMID 27888804, 2016). "Entangled crosstalk between Wnt and other signaling pathways (i.e. Notch and STAT3) triggered other signaling pathways involved in cancer initiation, progression, and metastasis." (PMID 27259262, 2016). "The signal transducer and activator of transcription 3 (STAT3) is a common transcriptional regulator, whose aberrant expression has been widely found in human cancers, including PC." (PMID 27577070, 2016). "The PIAS3 transcript is rarely detected in certain cancers such as mesotheliomas and lymphoma cells, and loss of PIAS3 expression is responsible for constitutive STAT3 activation." (PMID 26768588, 2016). "Previous studies revealed that CD24 mediated gastric carcinogenesis and promoted cancer cell progression via STAT3 activity, and regarded various CD24-mediated genes as STAT3 target genes." (PMID 27494878, 2016). "Generally activated via growth factor and cytokine signaling, STAT3 can transcriptionally drive oncoproteins, pro-survival and pro-proliferative proteins as well as angiogenic factors, thereby contributing to cancer." (PMID 27458446, 2016). "At the same time, lncRNA-ATB upregulates interleukin-11 (IL-11) and activates IL-11/STAT3 (signal transducer and activator of transcription 3) signaling, which enables cancer cell colonization." (PMID 26989421, 2016). "In recent evidence from previous studies, STAT3 was constitutively activated in some types of cancer." (PMID 27504822, 2016). "The signaling intensity of Rluc therefore indicated the Stat3 signaling activation in 4T1 cancer cells." (PMID 27460364, 2016). "Persistent phosphorylation of STAT3 has been found in numerous malignant neoplasms, such as head and neck cancers." (PMID 26784960, 2016).